BRCC3 (BRCA1/BRCA2-containing complex subunit 3)
Diseases named in the same sentence as BRCC3 in open-access papers (continued):
Sharing a sentence is not in itself a finding about the gene and the disease.
glioma (4 papers, 2014 to 2023). A benign or malignant brain and spinal cord tumor that arises from glial cells (astrocytes, oligodendrocytes, ependymal cells). "A previous study demonstrated that BRCC3 gene knockdown caused a decline in the migration and invasion capabilities of glioma cells." (PMID 26024915, 2015). "The increase in phosphorylated H2AX foci (γH2AX) formation, an indicator of DNA damage, persisted in TMZ-treated glioma cells with stable knockdown BRCC3 expression, suggesting that BRCC3 gene deficiency is associated with DNA repair impairment." (PMID 25337721, 2014). "Thus, effectively inhibiting BRCC3 expression in order to cause an insufficiency of homology-directed repair in glioma cells is a potential therapeutic strategy for sensitizing glioma tumor cells to the alkylating anti-tumor drugs." (PMID 25337721, 2014). "Through our previous study in genome-wide cDNA expression profiling on tumorigenic C6 glioma cells, we found that tumorigenic C6 glioma cells showed abundant amount of BRCC3." (PMID 25337721, 2014). "To gain insights into the functional role of BRCC3 in glioma cells, we examined glioma cell growth by inhibition of BRCC3 expression in U251 and A172 cells." (PMID 25337721, 2014). "We previously found that BRCA1-BRCA2-containing complex subunit 3 (BRCC3) was highly expressed in tumorigenic rat glioma cells." (PMID 25337721, 2014). "Given the fact that BRCC3 is a component of BRCA complex involved in HR-dependent DNA repair for DNA damage, BRCC3 mRNA expression in these three glioma cell lines was examined." (PMID 25337721, 2014). "Here, to elucidate the functional role of BRCC3 in DNA repair pathway induced by TMZ, we have generated the glioma cell lines with stable BRCC3 gene knockdown." (PMID 25337721, 2014). "Our findings provide the important evidence showing that targeting BRCC3 expression can impair DNA repair in U251 and A172 cells and increases sensitization of the glioma cells to the alkylating drugs." (PMID 25337721, 2014). "To determine the functional role of BRCC3 in glioma cells, we first examined the expression of BRCC3 in human glioma tissues." (PMID 25337721, 2014). "The findings point to BRCC3 as a potential target for treatment of alkylating drug-resistant glioma." (PMID 25337721, 2014). "Through the analysis of one-way ANOVA, we found that BRCC3 immunoreactivity score (IRS) was significantly correlated to various grades of glioma (F = 6.0647, p = 0.00295)." (PMID 25337721, 2014). "Given the findings that HR-DNA repair proteins (BRCA1, BRCA2 and RAD51) are significantly increased in TMZ-resistant glioma cells, an abundance expression of BRCC3 in glioma cells seems likely to foster HR-dependent DNA repair processes." (PMID 25337721, 2014). "This supports our view that BRCC3 upregulation is common response to protect glioma cells against alkylating agent-induced DNA damage." (PMID 25337721, 2014). "The morphological examination showed that the inhibition of BRCC3 expression induced the elongation of these glioma cell processes (arrows)." (PMID 25337721, 2014). "In summary, we demonstrate that by inducing DNA repair, BRCC3 renders glioma cells resistant to TMZ." (PMID 25337721, 2014). "BRCC3 led to the resistance of glioma cells to temozolomide." (PMID 37564930, 2023). "Moreover, the expression of BRCC3 in the two glioma cell lines is upregulated in response to TMZ or BCNU." (PMID 25337721, 2014). "Nevertheless, the role of BRCC3 in glioma cells remains elusive." (PMID 25337721, 2014). "Given that the formation of γH2AX foci is correlated to cell senescence, we have also examined if the inhibition of BRCC3 gene expression could lead to glioma cell senescence." (PMID 25337721, 2014). "Moreover, we found no significant change in the expression of genes associated DNA repair in mock and BRCC3-KD glioma cells without TMZ treatment (data no shown)." (PMID 25337721, 2014).
glioma (continued). "Thus, the inhibition of BRCC3 expression may impair DNA repair mechanism in U251 and A172 cells, which can promotes sensitization of the two glioma cell lines to TMZ." (PMID 25337721, 2014). "However, the functional role of BRCC3 in human glioma cells remains to be characterized." (PMID 25337721, 2014). "Moreover, the IRS of BRCC3 in grade IV GBM tissues was higher than normal cortical tissues, indicating that the high level of BRCC3 expression is associated with tumor cell growth during glioma progression." (PMID 25337721, 2014). "The inhibition of BRCC3 gene expression significantly reduces the cell viability and clonogenicity of U251 and A172 cells by TMZ treatment, indicating that BRCC3 can be treated as the target in order to enhance the sensitivity of glioma cells to TMZ." (PMID 25337721, 2014). "In addition, we show that two glioma cell lines, which derived from patients with grade IV malignant glioma and GBM, U251 and A172 cells, had abundant expression of BRCC3 mRNA." (PMID 25337721, 2014). "In summary, BRCC3 is involved in the regulation of cell growth and TMZ resistance in glioma cells." (PMID 25337721, 2014). "The action of Mcl-1/Bak axis on TMZ-induced cell death of BRCC3-KD glioma cells is not yet known." (PMID 25337721, 2014). "However, similar levels of γH2AX foci formation are observed in mock and BRCC3-KD glioma cells in the absence of TMZ, indicating no serious DNA damage in BRCC3-KD cells without TMZ." (PMID 25337721, 2014). "Thus, it remains to be further dissected if the DUB activity of cytosolic BRCC3 manipulates glioma cell growth in the absence of alkylating agents." (PMID 25337721, 2014). "Notably, BRCC3 is predominantly observed in the cytoplasm of glioma cells without TMZ treatment." (PMID 25337721, 2014).
hepatocellular carcinoma (4 papers, 2024 to 2025). A malignant tumor that arises from hepatocytes. "For instance, the BRCA1/BRCA2-containing complex subunit 3 (BRCC3; also known as BRCC36) deubiquitinates HMGCR, a process dependent on deubiquitinating enzyme (DUB) activity, thereby inhibiting ferroptosis in human hepatocellular carcinoma cells while promoting cellular pyroptosis." (PMID 38844964, 2024).
gastric cancer (3 papers, 2022 to 2024). A primary or metastatic malignant neoplasm involving the stomach. "LncRNA TMPO-AS1/miR-126-5p/BRCC3 axis promotes gastric cancer growth and angiogenesis by activating the PI3K/Akt/mTOR pathway." (PMID 39605891, 2024). "Another study explored the effect of TMPO-AS1 on gastric cancer and showed that TMPO-AS1 facilitated cell proliferation, cell migration, and angiogenesis in gastric cancer cells by targeting the miR-126-5p/BRCC3 axis to regulate the PI3K/Akt/mTOR pathway." (PMID 35040749, 2022).
Hypergonadotropic hypogonadism (3 papers, 2018 to 2025). Reduced function of the gonads (testes in males or ovaries in females) associated with excess pituitary gonadotropin secretion and resulting in delayed sexual development and growth delay. "Moyamoya Disease 4, characterised by a short stature, hypergonadotropic hypogonadism and facial dysmorphism (MYMY4, OMIM #300845), also referred to as BRCC3‐associated moyamoya syndrome, has so far been described in 11 individuals." (PMID 39552268, 2025). "As MMS in IV.4 was also associated with hypergonadotropic hypogonadism, we first carried out array CGH analysis to investigate the hypothesis of a BRCC3 loss-of-function mutation, identifying a 47,XXY karyotype compatible with patient’s clinical features." (PMID 30001348, 2018).
nasopharyngeal carcinoma (3 papers, 2015 to 2024). A carcinoma arising from the nasopharyngeal epithelium. "Elevated levels of BRCC3 have been reported in nasopharyngeal carcinoma and high BRCC3 expression is associated with radio-resistance and poor survival of nasopharyngeal carcinoma patients." (PMID 32560247, 2020). "High BRCC3 expression in nasopharyngeal carcinoma patients is associated with poor survival." (PMID 26024915, 2015). "For example, in nasopharyngeal carcinoma,BRCC3 knockdown increased cell survival, attenuated DNA damage repair, and led to G2/M cell cycle arrest in radioresistant nasopharyngeal carcinoma cells." (PMID 38449391, 2024). "The expression of BRCC3 was much higher in radioresistant nasopharyngeal carcinoma cells than in radiosensitive cells." (PMID 26024915, 2015). "BRCC3 expression of nasopharyngeal carcinoma cell lines was determined by Western-blotting and real-time PCR." (PMID 26024915, 2015). "Immunohistochemical analysis of BRCC3 was carried out in 100 nasopharyngeal carcinoma tissues, and the protein level was correlated to patient survival." (PMID 26024915, 2015). "To study the clinical application value of BRCC3, we determined the relationship between the BRCC3 expression level and nasopharyngeal carcinoma patient survival." (PMID 26024915, 2015). "The contribution of BRCC3 to nasopharyngeal carcinoma prognosis and radiosensitivity is still unclear." (PMID 26024915, 2015). "The BRCC3 protein level was inversely correlated with nasopharyngeal carcinoma patient overall survival (P < 0.001) and 3-year loco-regional relapse-free survival (P = 0.034)." (PMID 26024915, 2015). "Additionally, the effects of BRCC3 knockdown on nasopharyngeal carcinoma cell clongenic survival, DNA damage repair, and cell cycle distribution after irradiation was assessed." (PMID 26024915, 2015). "Regulation of the cell cycle may be another important mechanism for radiosensitization, as supported by our results that BRCC3 disruption increased cell-cycle arrest in nasopharyngeal carcinoma cell lines." (PMID 26024915, 2015). "Moreover, we investigated the contribution of BRCC3 to radiation resistance in HNE1 and CNE2R cells, two human nasopharyngeal carcinoma cell lines that expressed a high level of BRCC3 and exhibited resistance to radiation." (PMID 26024915, 2015). "BRCC3 knockdown could abate the radioresistance in nasopharyngeal carcinoma cells." (PMID 26024915, 2015).
Cerebral ischemia (2 papers, 2023 to 2024). Restriction of arterial blood supply to the brain associated with insufficient oxygenation to support the metabolic requirements of the tissue. "confirm that BRCC3 plays a crucial role in the activation of NLRP6 inflammasome and inflammasome‐associated inflammatory response and pyroptosis in cerebral ischemia/reperfusion injury." (PMID 38544474, 2024). "Moreover, as a regulator of the ubiquitination and activity of NLRP3, BRCC3 was activated following cerebral ischemia and TENS treatment reversed the promoted BRCC3 levels induced by ischemic condition." (PMID 37101593, 2023).
cervical cancer (2 papers, 2023 to 2024). A primary or metastatic malignant neoplasm involving the cervix. "In cervical cancer, interference with BRCC3 inhibited cervical cancer cell viability, invasion and migration ability." (PMID 38449391, 2024). "Downregulation of BRCC3 inhibited cell proliferation and metastasis by inhibiting EMT of cervical cancer cells." (PMID 37564930, 2023).
ischemic stroke (2 papers, 2023 to 2024). A stroke disorder caused by obstruction of blood flow to the brain, due to thrombotic (local blood clot formation) or embolic (due to a blood clot or other material traveling from another site) event. "Studies have shown that TEAS, by adjusting the SIRT1/FOXO3a and SIRT1/BRCC3/NLRP3 signaling pathways following ischemic stroke, inhibits cell apoptosis, oxidative stress, and inflammation of the nerve to reduce brain damage and accelerates the recovery of neurons and some functional metabolism." (PMID 39665041, 2024). "In conclusion, our results indicated that TENS alleviated brain damage following ischemic stroke via inhibiting neuronal oxidative stress and pyroptosis and activating mitophagy, possibly via the regulation of TXNIP, BRCC3/NLRP3, and HIF-1α/BNIP3 pathways." (PMID 37101593, 2023). "However, the precise alteration in BRCC3 levels and whether TENS exerts counteracting effects on oxidative stress and inflammasomes by TXNIP and BRCC3/NLRP3 signaling have barely been investigated in ischemic stroke." (PMID 37101593, 2023).
liver cancer (2 papers, 2024 to 2025). An epithelial or non-epithelial malignant neoplasm that arises from the liver. "Additionally, immunofluorescence co-localization showed that TFPI2, CCAR2, and BRCC3 had clear co-localization in liver cancer cells." (PMID 40765823, 2025).
myelodysplastic syndrome (2 papers, 2020). A clonal hematopoietic disorder characterized by dysplasia and ineffective hematopoiesis in one or more of the hematopoietic cell lines. "While recurrent mutations in BRCC3 have been recently described in myelodysplastic syndromes (MDS), only one BRCC3 mutation has been identified in a patient with complex karyotype in the TCGA AML cohort of 200 cases." (PMID 31576005, 2020). "Recurrent mutations in BRCC3 have been reported in myelodysplastic syndromes (MDS) but not in de novo AML." (PMID 31576005, 2020). "While mutations in BRCC3, a metalloprotease implicated in DNA repair, have been recurrently reported in myelodysplastic syndromes (MDS) and AML23,24, they have not previously been reported in MF." (PMID 31911629, 2020).
astrocytoma (1 paper, 2014). "The results from immunohistochemistry indicated that tumor cells in grade I-III astrocytoma and grade IV GBM displayed a strong BRCC3 immunoreactivity (arrows), whereas BRCC3 staining was weak in normal brain tissues (arrows)." (PMID 25337721, 2014). "Here, we provide the evidence that the level of BRCC3 expression is much higher in GBM tumor cells compared to normal human brain tissues, and grade I-II astrocytoma." (PMID 25337721, 2014).
cleft lip (1 paper, 2021). Congenital defect in the upper lip where the maxillary prominence fails to merge with the merged medial nasal prominences. "In particular, they highlight an increased gene dosage in BRCC3 as a possible alteration underlying cleft lip and cleft palate development, warranting future probing of this locus in non-syndromic cleft lip or palate cases." (PMID 34199727, 2021). "Interestingly, it has been previously reported twice that certain non-syndromic forms of cleft lip and cleft palate are linked to alterations in the BRCA1 and BRCA2 genes, whose products interact directly with BRCC3 in mediating their physiological effects." (PMID 34199727, 2021).
colitis (1 paper, 2021). Inflammation of the colon. "Using the DSS-colitis model, they found that mice bearing NLRP3-R779C mutation in hematopoietic cells showed intensified colitis, which was ameliorated by downregulation of BRCC3 or JOSD2." (PMID 33808793, 2021).
coronary heart diseases (1 paper, 2016). "Monogenic diseases stochastically associated with MMD are often accompanied by coronary heart diseases (CHD) (BRCC3 and ACTA2)." (PMID 26662949, 2016).
glioblastoma (1 paper, 2014). The most malignant astrocytic tumor (WHO grade IV). "In addition, it is possible that BRCC3 effect could combine with other factors associated with TMZ resistance in glioblastoma, such as EFEMP1 (Fibulin-3), an extracellular matrix protein." (PMID 25337721, 2014). "This study indicated that the upregulation of BRCC3 expression was induced in two human malignant glioblastoma U251 and A172 cell lines following exposure to the alkylating agent, temozolomide (TMZ)." (PMID 25337721, 2014).
Hepatitis (1 paper, 2023). Inflammation of the liver. "To investigate the role of BRISC in LPS-induced inflammatory liver diseases, we established a mouse model of D-GalN/LPS-induced fatal hepatitis in global ABRO1 and BRCC3 knockout mice." (PMID 37968261, 2023).
Hypercholesterolemia (1 paper, 2024). An increased concentration of cholesterol in the blood. "Our present findings suggest that these distinct mechanisms of JNK activation converge on BRCC3 and NLRP3 in hypercholesterolemia and TET2 CH resulting in synergistic NLRP3 activation." (PMID 38522750, 2024).
leukemia (1 paper, 2023). A malignant (clonal) hematologic disorder, involving hematopoietic stem cells and characterized by the presence of primitive or atypical myeloid or lymphoid cells in the bone marrow and the blood. "Another CN-LOH region of interest was identified in sample S5, showing CN-LOH of Xq25–qter, involving four genes (STAG2, BCORL1, PHF6, and BRCC3) that have previously been implicated in different types of leukemias." (PMID 36831635, 2023).
malignant glioma (1 paper, 2014). A grade III or grade IV glioma arising from the central nervous system. "In this study, we investigated the biological function of BRCC3 in two human malignant glioma (MG) cell lines, U251 and A172 cells that expressed a high level of BRCC3 mRNA and exhibited resistance to TMZ." (PMID 25337721, 2014).
osteoporosis (1 paper, 2019). A condition of reduced bone mass, with decreased cortical thickness and a decrease in the number and size of the trabeculae of cancellous bone (but normal chemical composition), resulting in increased fracture incidence. "We identified three hub genes that might associate with osteoporosis including BRCC3, UBE2N, and UBE2K." (PMID 30834083, 2019). "Then, three hub genes that have strong protein and protein interactions and might be associated with osteoporosis were identified, including BRCC3, UBE2N, and UBE2K." (PMID 30834083, 2019). "In this study, we found BRCC3 mRNA and β-catenin mRNA were significantly increased in osteoblast isolated from osteoporosis patients." (PMID 30834083, 2019). "Depletion of BRCC3 promoted the activation of alkaline phosphatase and formation of calcified nodules in osteoblasts isolated from osteoporosis patients and up-regulated β-catenin expression." (PMID 30834083, 2019). "In summary, BRCC3 is an important regulator for osteogenic differentiation of osteoblasts through β-catenin signaling, and it might be a promising target for osteoporosis treatment." (PMID 30834083, 2019). "BRCC3 is an important regulator for osteogenic differentiation of osteoblasts through β-catenin signaling, and it might be a promising target for osteoporosis treatment." (PMID 30834083, 2019). "UBE2N mRNA and UBE2K mRNA were not changed in osteoblasts isolated from osteoporosis patients, compared with healthy donors, whereas BRCC3 mRNA was significantly increased." (PMID 30834083, 2019). "The mRNA expressions of UBE2N and UBE2K not changed in osteoblasts from osteoporosis patients compared with healthy donors, while the mRNA expression of BRCC3 was significantly increased." (PMID 30834083, 2019).
pancreatic cancer (1 paper, 2023). "Our study was the first to report the function of BRCC3 in pancreatic cancer, which found that downregulation of BRCC3 inhibited the cell proliferation, metastasis and induced apoptosis." (PMID 37564930, 2023). "In conclusion, UCA1 acted as an oncogene in pancreatic cancer by partly regulating miR-582-5p/BRCC3, which promoted cell proliferation, migration, and inhibited apoptosis." (PMID 37564930, 2023). "UCA1 acted as an oncogene in pancreatic cancer by partly regulating miR-582-5p/BRCC3, which could be a new therapeutic target for pancreatic cancer." (PMID 37564930, 2023). "Compared with pancreatic cancer cells with UCA1 inhibitors only, cells were co-transfected with si-UCA1 and pc-BRCC3 (a plasmid for upregulation of BRCC3) showed increased cell proliferation and metastasis, and decreased in apoptosis." (PMID 37564930, 2023).
peritonitis (1 paper, 2023). Inflammation of the peritoneum (tissue that lines the abdominal wall and covers most of the organs in the abdomen). "A later study revealed that BRCC3 deficiency attenuates NLRP3‐associated inflammatory diseases such as peritonitis and sepsis." (PMID 37361896, 2023).